PREPL (prolyl endopeptidase like)
Description:
Serine peptidase whose precise substrate specificity remains unclear. Does not cleave peptides after a arginine or lysine residue. Regulates trans-Golgi network morphology and sorting by regulating the membrane binding of the AP-1 complex. May play a role in the regulation of synaptic vesicle exocytosis.
Synonyms: KIAA0436; CMS22
Tractability: PROTAC: ubiquitination databases record sites on it; its protein half-life has been measured.
Target class: Enzyme
Gene: Protein-coding gene on chromosome 2 (44,316,281 to 44,361,862, reverse strand). Ensembl gene ENSG00000138078.
Subcellular location: Cytoplasm, cytosol; Golgi apparatus, trans-Golgi network; Cytoplasm, cytoskeleton; Golgi apparatus; Nucleus
Gene Ontology:
Molecular function: peptidase activity; serine-type endopeptidase activity; serine-type peptidase activity
Biological process: regulation of synaptic vesicle exocytosis; Golgi to plasma membrane protein transport; retrograde transport, endosome to Golgi; proteolysis
Cellular component: mitochondrion; nucleus; cytoskeleton; Golgi apparatus; trans-Golgi network; cytosol
Genetic constraint (gnomAD): Loss-of-function variants: 69 observed, 67.6 expected, observed/expected ratio (o/e) 1.02, 90% interval 0.84 to 1.25. The upper end of that interval is the gene's LOEUF score, 1.25, which puts it in group 5 of 6, group 1 being the genes least tolerant of losing a copy. Missense variants: 971 observed, 784.63 expected, observed/expected ratio (o/e) 1.24, 90% interval 1.17 to 1.3. Synonymous variants: 308 observed, 271.81 expected, observed/expected ratio (o/e) 1.13, 90% interval 1.03 to 1.25.
Homologues: Orthologues: chimpanzee PREPL (99% identical), macaque PREPL (99% identical), dog PREPL (97% identical), rabbit PREPL (97% identical), pig PREPL (96% identical), guinea pig PREPL (94% identical), mouse Prepl (94% identical), rat Prepl (94% identical), tropical clawed frog prepl (45% identical), zebrafish prepl (40% identical), Drosophila melanogaster CG5355 (21% identical), Drosophila melanogaster CG2528 (18% identical). Paralogues in human: PREP (19% identical).
Diseases named in the same sentence as PREPL in open-access papers:
PREPL is named in the same sentence as 14 diseases in open-access papers, as found by Europe PMC text mining. Sharing a sentence is not in itself a finding about the gene and the disease. The quoted sentences say what the papers report.
cystinuria (7 papers, 2012 to 2024). Cystinuria is a renal tubular amino acid transport disorder characterized by recurrent formation of kidneys cystine stones. "In humans a deletion of the 2p21 region including four genes (PP2Cβ, SLC3A1, PREPL and CAMKMT) was described as a syndrome (MIM #606,407) associated with cystinuria, intellectual disability, mitochondrial disease, hypotonia and facial dysmorphism." (PMID 31865460, 2020). "In contrast to the association of SLC3A1 mutations with cystinuria, variants restricted to PREPL causing an “isolated hypotonia” phenotype have not yet been reported." (PMID 22480232, 2012). "Homozygous deletion of both PREPL and the neighboring gene SLC3A1 result in Hypotonia-cystinuria syndrome (AR inheritance, OMIM phenotype number 606407) with hypotonia, cystinuria, and cystine NL." (PMID 38606357, 2024). "A further study of new families presenting with cystinuria-hypotonia found that in some patients only SLC3A1 and PREPL were deleted, while PPM1B and C2orf34 remained unaffected." (PMID 36313552, 2022). "The absence of the CaM KMT activity can thus contribute to the mental retardation and mitochondrial defect observed in the 2p21 deletion patients but not in the hypotonia cystinuria patients with the absence of only the SLC3A1, PREPL alone." (PMID 23285036, 2012).
Hypotonia (6 papers, 2012 to 2022). Hypotonia is an abnormally low muscle tone (the amount of tension or resistance to movement in a muscle). "The raw WES data were evaluated for copy number variants in the SLC3A1 and PREPL genes and revealed a homozygous deletion in this region that could be confirmed by Sanger sequencing and led to the diagnosis of hypotonia-cystinuria syndrome." (PMID 25735936, 2015). "Interest in the prolyl endopeptidase-like gene (PREPL) was sparked by the discovery that this gene associated with 2p21 deletion syndrome and also with hypotonia-cystinuria syndrome (HCS)." (PMID 24586561, 2014). "Prolyl endopeptidase-like (PREPL) is an uncharacterized member of the prolyl peptidase family that was discovered because of its deletion in humans with hypotonia-cystinuria syndrome (HCS)." (PMID 24586561, 2014). "Deletion of the PREPL (prolyl endopeptidase-like) gene was detected in patients with congenital myastemic syndrome 22 (CMS22), and, together with the neighboring SLC3A1 gene, the PREPL gene is deleted in patients with hypotonia–cystinuria syndrome (HCS)." (PMID 32630529, 2020).
hypotonia-cystinuria syndrome (6 papers, 2012 to 2020). A rare syndrome including neonatal and infantile hypotonia and failure to thrive, cystinuria type 1 and nephrolithiasis, growth retardation due to growth hormone deficiency, and minor facial dysmorphism. "Hypotonia-cystinuria syndrome (HCS) associated with combined mutations in PREPL and SLC3A1 (a contiguous gene to PREPL on chromosome 2p21) comprises type A cystinuria, growth hormone deficiency, and fatigable muscle weakness." (PMID 29874875, 2018). "The second disorder is atypical hypotonia-cystinuria syndrome (HCS) caused by a smaller deletion of 77.4 kb on the 2p21 chromosome that encompasses SLC3A1, PREPL and similarly to the first report the first exon of CaM KMT." (PMID 23285036, 2012). "Hypotonia-Cystinuria syndrome (HCS) is a rare disease, caused by a mutation in two contiguous genes (SLC3A1 and PREPL) localized on chromosome 2p21, and it is characterized by both renal involvement with cystine stones and nervous involvement with hypotonia." (PMID 31024870, 2019). "In addition to isolated cystinuria, patients suffering from the hypotonia-cystinuria syndrome have been reported carrying deletions including at least the SLC3A1 and the PREPL genes in 2p21." (PMID 22480232, 2012).
PREPL deficiency (2 papers, 2019 to 2020). "Here we report a Chinese female with isolated PREPL deficiency, who carried a novel splicing mutation (c.616 + 1G > T) in the PREPL gene." (PMID 32218803, 2020). "In conclusion, we identified a point homozygous mutation (c.616 + 1G > T) in the PREPL gene in a Chinese girl with typical PREPL deficiency." (PMID 32218803, 2020). "Mutations in the PREPL gene cause isolated PREPL deficiency." (PMID 30808424, 2019). "Therefore, this mutation of the PREPL gene is pathogenic and leads to a PREPL deficiency phenotype." (PMID 32218803, 2020).
glioblastoma (1 paper, 2021). The most malignant astrocytic tumor (WHO grade IV).
Parkinson disease (1 paper, 2020). A progressive degenerative disorder of the central nervous system characterized by loss of dopamine producing neurons in the substantia nigra and the presence of Lewy bodies in the substantia nigra and locus coeruleus. "Even so, taking the PREPL expression, its cellular localization pattern, and the strong parallel with POP, concerning the interaction with α-Syn, the results described in the present work put PREPL as another target for drugs aiming to treat synucleinopathies (e.g., Parkinson’s disease)." (PMID 32630529, 2020).
synucleinopathies (1 paper, 2020). "Therefore, given the attention to POP inhibitors as potential drugs to treat synucleinopathies, the present data point to PREPL as another potential target to be explored for this purpose." (PMID 32630529, 2020).
mitochondrial disease (2 papers, 2020 to 2021). "In contrast, the presence of mitochondrial disease is relatively common in “2p21 microdeletion syndrome” which involves the deletion of at least four contiguous genes on chromosome 2, SLC3A1, PREPL, PPM1B, and CAMKMT." (PMID 34612606, 2021).
cancer (1 paper, 2025). A tumor composed of atypical neoplastic, often pleomorphic cells that invade other tissues. "Other genes, such as PREPL (prolyl endopeptidase-like—usually involved in neurological and metabolic pathways) and MTURN (a neural progenitor differentiation regulator associated with cancer progression), emerged as potential biomarkers influencing survival outcomes." (PMID 40559081, 2025).
genetic disorder (1 paper, 2024). "Congenital myasthenic syndrome-22 (CMS22, OMIM 616224) is a rare genetic disorder caused by deleterious genetic variation in the prolyl endopeptidase-like (PREPL) gene." (PMID 39078710, 2024).
PREPL also shares sentences with these, for which no sentence is quoted: congenital myasthenic syndrome (3 papers); Anxiety (1); Hypergonadotropic hypogonadism (1); Intellectual disability (1).